RPS2P25 (ribosomal protein S2 pseudogene 25)
Gene: Processed pseudogene on chromosome 5 (85,762,559 to 85,763,138, forward strand). Ensembl gene ENSG00000241965.
Diseases named in the same sentence as RPS2P25 in open-access papers:
RPS2P25 is named in the same sentence as 1 disease in open-access papers, as found by Europe PMC text mining. Sharing a sentence is not in itself a finding about the gene and the disease. The quoted sentences say what the papers report.
prostate carcinoma (1 paper, 2024). A carcinoma that arises from epithelial cells of the prostate gland. "Under these conditions, several SNPs were detected near genes (LINC01824, TRIML2, and RPS2P25) by GWAS that may be associated with the development of prostate cancer." (PMID 38406143, 2024).